CAT (catalase)
Diseases named in the same sentence as CAT in open-access papers (continued):
Sharing a sentence is not in itself a finding about the gene and the disease.
Hepatic steatosis (continued). "CAT overexpression reduces 13-HODE-induced liver steatosis and protects male mice against age-related liver steatosis." (PMID 38071367, 2023). "Lower enzyme activities of SIRT1, PGC-1α, Cu/Zn SOD, CAT, GSH-Px, SREBP-1c and Mn SOD (p < 0.05) and concentration of reactive oxygen species (ROS) were observed in dairy cows with fatty liver." (PMID 32230804, 2020). "It reduces liver steatosis by downregulating the lipogenic genes (acetyl-CoA carboxylase (ACC1), FAS, and SREBP-1c) and enhances antioxidant defense by increasing superoxide dismutase (SOD), catalase (CAT), and glutathione peroxidase (GPx) activity." (PMID 40218971, 2025). "Outcomes measured at baseline and post-intervention included anthropometrics, liver enzymes, metabolic profile, hepatic steatosis (CAP score), inflammatory markers (TNF-α, MDA), antioxidant enzymes (SOD, CAT), and lifestyle behaviors (physical activity, sleep)." (PMID 40988029, 2025). "DOP increased the levels of GLP-1, High-density lipoprotein cholesterol (HDL-C), alleviated hepatic oxidative damage and reduced hepatic steatosis by elevating the levels of superoxide dismutase (SOD), catalase (CAT), and glutathione (GSH), and by lowering the level of MDA." (PMID 40363788, 2025). "Considering the high antioxidant potential of GSE and the role of inflammation and oxidative stress in NAFLD, GSE affects the severity of hepatic steatosis by reducing inflammatory factors such as hs-CRP, TNF-α, and oxidative stress (MDA), as well as increasing antioxidant enzymes (SOD and CAT)." (PMID 38755622, 2024). "First, haw pectin improved hepatic steatosis by ameliorating hepatic oxidative stress injury by increasing the tissue reserves of superoxide dismutase (SOD), catalase (CAT), glutathione (GSH), and total antioxidant capacity (TAC), which had been depleted by a high-fat diet in Kunming mice." (PMID 35215517, 2022). "Liver steatosis and exposure to H2O2 may also activate membrane NADPH oxidase (NOX), which catalase the process of superoxide anion formation." (PMID 33510844, 2021). "Treatment of hepatic steatosis by BDS (450 mg/kg), PDS (30 mg/kg), CDS (30 mg/kg), or ZH (250 μg/kg) modulated the hepatic level of catalase by 1, 1.3, 1.7, and 2 folds' elevation, respectively; and the hepatic level of GST by about 0.8, 1, 1.2, and 1.3 folds' elevation, respectively." (PMID 32420546, 2020). "The simultaneous upregulation of peroxidases CAT and GPX3 and the downregulation of antioxidant enzymes GSH, accompanied by elevated levels of MDA, HNE, HODE, and oxoODE, jointly indicate a close relationship between the peroxidation of FFA and hepatic steatosis (route 3)." (PMID 38837944, 2024). "Curcumin treatment alleviates the severity of hepatic steatosis by blocking the NF-κB signaling pathway through the inhibition of O-GlcNAcylation and enhancing antioxidant systems, including SOD1 (superoxide dismutase 1), GPx (glutathione peroxidase), and CAT (catalase)." (PMID 37375652, 2023).
neuroblastoma (31 papers, 2009 to 2025). Neuroblastoma (NB) is the most common solid, extracranial childhood tumor. "TRF pre-treatment in 6-OHDA-induced neuroblastoma cells ↑ cell viability, ↓ ROS generation and CAT activity, ↑ SOD activity, and ↑ dopamine receptor D2 gene expression compared to the untreated groups (treated with 6-OHDA without TRF supplementation)." (PMID 40869012, 2025). "The antioxidant activity of the new models was tested through superoxide dismutase and catalase probes in conjunction with the studies about their neuroprotective effects in human SH-SY5Y neuroblastoma cells in an oxidative stress model." (PMID 38539799, 2024). "STS has been reported to enhance CAT activity and the protein level of CAT in human neuroblastoma cells." (PMID 37697234, 2023). "For example, inhibition of sodium nitroprusside-mediated NO release and increased production of transcripts coding for antioxidant enzymes (i.e., SOD1, GPx1 and CAT) have been reported upon melatonin treatment in neuroblastoma cells and HUVEC, respectively." (PMID 35883714, 2022). "In this sense, the addition of red raspberry inhibited the apoptosis induction and ROS accumulation by enhancing the activity of catalase in H2O2-treated SH-SY5Y neuroblastoma cells." (PMID 34071973, 2021). "In order to determine the effect of the compound on the activity of catalase, human neuroblastoma cells were incubated with 10 μM TBHP and compound 5 for 6 h." (PMID 27801775, 2016). "In neuroblastoma cells, ROS generation induced by 5–10 μM ATRA caused lipid peroxidation and interplay between catalase, and ATRA was found during macrophage differentiation." (PMID 25140197, 2014). "Our results show that the increase in the enzymatic activities of SOD, GPx, and CAT in neuroblastoma cells incubated with rotenone alone is likely due to a response towards increased ROS generation following rotenone treatment." (PMID 24205431, 2013). "Indeed, as catalase is the enzyme catalyzing the decomposition of H2O2 to water and oxygen, the observed in vivo enhancement of scopolamine-decreased catalase activity by 5MeO closely matches the beneficial effect of the substance in neuroblastoma cells." (PMID 39683869, 2024). "In addition, studies have shown that catalase-Aβ peptide interaction and colocalization decreased the efficiency of catalase in offsetting cellular damage induced by the ROS intermediate H2O2 in a human neuroblastoma cell line." (PMID 29707568, 2018). "Emetine cytotoxicity could be prevented by the antioxidants L-ascorbic acid, L-cysteine, reduced glutathione, thiourea, deferoxamine, 1,3-dimethylthiourea and catalase in astrocytoma cells or by reduced glutathione in neuroblastoma cells, indicating an oxidative stress-mediated cell death mechanism." (PMID 38684672, 2024). "PL extract has dose-dependent protective effects on oxidative stress-induced apoptosis by diminishing Cleaved caspase-3 and ROS levels and increasing the expression of HO-1, CAT, and SOD in SK-N-MC cells, a human neuroblastoma cell line." (PMID 34203617, 2021). "Consistent with our observation, mRNA expression levels of many antioxidant genes including SODs, CAT and HMOX were found to be increased along with the gradual increase of cellular H2O2 level in the Tat treated human neuroblastoma cells (SH-SY5Y)." (PMID 31608139, 2019). "In human SH-SY5Y neuroblastoma cells, a 24 h a 50 Hz, 1 mT ELF-MF exposure significantly limited the H2O2-induced increase of catalase, whose catalysis ensures a rapid removal of hydrogen peroxide from the cell." (PMID 29527520, 2018). "We have recently demonstrated that human neuroblastoma cells respond to a long-term 50 Hz, 1 mT ELF-MF by increasing CAT- and GPX-based scavenging activities, as well as by improving the availability of reduced glutathione." (PMID 29527520, 2018).
neuroblastoma (continued). "In this study we demonstrate for the first time that the FOXO3-regulated gene DEPP impairs ROS detoxification via the enzyme catalase and thereby increases the effects of ROS on FOXO3-induced apoptosis in neuroblastoma cells." (PMID 25261981, 2014). "Previous study also reported that decanoic acid reduces oxidative stress in neuroblastoma cells by activating enzyme activity of catalase but not its transcriptional level (Mett and Müller, 2021)." (PMID 36582526, 2022). "A trypsin-derived peptide fragment of ependymin activates the transcription factor, AP-1, in mouse neuroblastoma cells and increases the expression of the antioxidant enzymes superoxide dismutase (SOD), catalase (CAT), and glutathione peroxidase (GPX) in rat primary cortical cultures." (PMID 19597568, 2009).
Stroke (31 papers, 2015 to 2025). Sudden impairment of blood flow to a part of the brain due to occlusion or rupture of an artery to the brain. "SOD, GSH, NO, and catalase are integral to the body’s antioxidant defence systems, and their serum levels have been investigated as potential biomarkers for stroke severity and recovery." (PMID 40837372, 2025). "Key antioxidant markers such as Superoxide Dismutase (SOD), Glutathione (GSH), Catalase, and Nitric Oxide (NO) have garnered increasing attention for their potential role in mitigating the effects of oxidative stress in stroke." (PMID 40837372, 2025). "The concentration of serum BNDF, NE, ET, and glutamate, and peripheral blood SOD, ALB, HB, and CAT suggest the function improvement of stroke patients." (PMID 39355076, 2024). "Catalase has been shown to mitigate oxidative stress and has been widely studied as an effective antioxidant in aging diseases including stroke." (PMID 36829671, 2023). "In this study, we have shown the potential of exosome-based tPA and exosome-based tPA/catalase formulations as therapeutics for thrombolytic stroke." (PMID 36829671, 2023). "The present study preliminarily deduced that serum BDNF, NE, ET and glutamate, and peripheral blood SOD, ALB, HB, and CAT can be used as indicators of functional recovery in stroke patients." (PMID 37731856, 2023). "Previous studies have shown that tPA delivery followed by catalase nanoparticles promoted post-stroke therapy." (PMID 36829671, 2023). "In stroke model, supplementation with ethanolic extract of C. asiatica prevented brain injury through a restoration of glutathione level and augmentation of catalase, SOD and GPx activities in ischemic rat49." (PMID 34188145, 2021). "In our study, stroke patients had significantly decreased SOD activity levels with a concomitant increase in CAT activity compared with that of controls." (PMID 33126675, 2020). "Another study revealed that the concentration of CAT in hemolysates was significantly increased in stroke patients at a 3-month follow-up check." (PMID 33126675, 2020). "All stroke patients (groups A–C) had catalase activities significantly elevated compared to the controls." (PMID 27774120, 2016). "Reduced activity of catalase in stroke patients diminishes the effectiveness of deactivation of H2O2, which can freely diffuse across the mitochondrial membrane, and therefore increases oxidative stress." (PMID 25838867, 2015). "In our study we noticed that that catalase activity in erythrocytes of stroke patients was about 25% lower in comparison with a control group of healthy." (PMID 25838867, 2015). "This study identified a significant relationship between higher levels of SOD, GSH, and NO and improved stroke recovery, whereas catalase did not exhibit a meaningful association with stroke severity or functional outcomes." (PMID 40837372, 2025). "They found significantly elevated oxidative stress, mainly through increased levels of TBARS, and enhanced antioxidant activities such as GSH, glutathione peroxidase (GPx), superoxide dismutase SOD, and catalase (CAT) in the Stroke-COVID group compared to those with ischemic stroke alone." (PMID 40837372, 2025). "In comparison, our study focused on the relationship between antioxidant markers (SOD, GSH, NO, and CAT) and ischemic stroke severity and recovery, and we found that higher levels of SOD, GSH, and NO were associated with better recovery and less severe stroke outcomes." (PMID 40837372, 2025). "Indeed, some studies propose leveraging the compensatory antioxidant role of CAT by enhancing its activity as a potential therapeutic strategy for stroke patients." (PMID 40672462, 2025). "The concentration of serum BNDF, NE, ET and glutamate, and peripheral blood SOD, ALB, HB and CAT may suggest the function improvement of stroke patients." (PMID 37731856, 2023). "In addition, glutathione (GSH), catalase and heme oxygenase-1 (HO-1) reduced levels in various stroke models." (PMID 36232980, 2022).
Stroke (continued). "Likewise, A. borbonica polyphenols and caffeic acid were reported to improve other ROS-detoxifying enzymes including catalase, GPx and heme oxygenase-1 deregulated by hyperglycemic condition in a mouse model of stroke and cerebral endothelial cells." (PMID 35624723, 2022). "Various antioxidant therapeutic approaches, i.e. polyethylene glycol-conjugated SOD (PEG-SOD) and polyethylene glycol-conjugated CAT (PEG-CAT), underscore that timely interventions following stroke attenuate neuroinflammatory damage partially due to limiting the ROS generation." (PMID 34691061, 2021). "We hypothesize that single nucleotide polymorphisms (SNPs) in the SOD2, CAT, GPX4, NOS1 and NOS2 genes might be associated with altered susceptibility to oxidative stress and stroke development." (PMID 33808851, 2021). "We observed a statistically significant increased level of carbonyl groups in plasma proteins, decreased level of plasma protein thiol groups, decreased catalase activity in erythrocytes, and increased plasma protein 3-nitrotyrosine level in stroke patients in relation to control group." (PMID 25838867, 2015). "Therefore, combining exosomes’ inherent therapeutic effects with tPA and catalase could prove an added advantage for stroke therapy compared to conventional methods." (PMID 36829671, 2023). "The c.-89A > T (rs7943316) polymorphism of the CAT gene and no stroke risk." (PMID 33808851, 2021). "Therefore, the high levels of CAT activity observed in our stroke population may have potentiated the antioxidant defense mechanism against the increased production of ROS." (PMID 33126675, 2020). "They found that oxidative damage was highest within 24 hours of stroke onset, with elevated levels of lipid peroxides and antioxidant enzyme activities, such as SOD and catalase." (PMID 40837372, 2025). "After stroke, HBOT has been shown to decrease the activity of pro-oxidant enzymes, including malondialdehyde, and increase it of CAT and SOD." (PMID 39545965, 2024). "The Stroke-COVID group displayed notably elevated levels of GSH (p = 0.0139 *), GPx (p < 0.0001 ****), SOD (p = 0.0363 *), and CAT (p = 0.0237 *) activities." (PMID 38069113, 2023). "While TAC remained relatively stable between the two groups, the Stroke-COVID group exhibited significantly higher levels of GSH, GPx, SOD, and CAT activities." (PMID 38069113, 2023). "For peripheral blood biomarkers, it was found that the concentrations of nutritional indicators (ALB and HB) and antioxidant markers (CAT and SOD) significantly increased with the rehabilitation of stroke." (PMID 37731856, 2023). "In one study, it was shown that the pretreatment withHO decreases infarct volume, neurologic deficits scores,and mortality and increases CAT and SOD activities in ananimal model of stroke." (PMID 34308573, 2021). "Px (p < 0.0001) and CAT activity (p = 0.0004, p < 0.0001, respectively) were significantly enhanced in both the NWS and SWS of stroke patients compared to controls." (PMID 32679906, 2020). "We showed that the activity of antioxidant enzymes (catalase and salivary peroxidase) was significantly higher in both NWS and SWS of stroke patients, similarly to uric acid concentration." (PMID 32679906, 2020). "Stroke and stress biomarkers such as TBARS, SOD, CAT, and GSH levels decreased following MqBE/anthocyanin treatment in stroke model mice." (PMID 32825710, 2020). "Rg1 increased the activity or content of antioxidant enzymes SOD and catalase (CAT), as well as HO1, contributing to the histological and functional benefits after stroke." (PMID 31068769, 2019). "BCCAO is characterized by lower levels of SOD and catalase activity and lowered GSH levels compared to healthy mice, indicating the presence of intense cerebral oxidative stress in mice affected by stroke." (PMID 28468264, 2017). "Significant inverse correlations were found between SOD, GSH, and NO levels and stroke severity (p<0.05), but catalase showed no such correlation (p=0.513)." (PMID 40837372, 2025).
Stroke (continued). "Furthermore, CAT activity has been found to closely correlate with clinical outcomes in AIS patients, highlighting its potential role in stroke prognosis." (PMID 40672462, 2025). "In stroke patients, the antioxidant defense system has been studied concerning enzymes, including superoxide dismutase, catalase, and glutathione peroxidase, and nonenzymatic antioxidants such as ascorbic acid, α-tocopherol, carotenoids, and uric acid." (PMID 39334896, 2024). "Moreover, the enhanced antioxidant defense mechanisms in the Stroke-COVID group, characterized by increased GSH, GPx, SOD, and CAT activity, suggest a concerted effort to counteract the oxidative stress provoked by the dual insult." (PMID 38069113, 2023). "However, to titrate the excess ROS produced during a stroke, endogenous antioxidants such as SOD and catalase are crucial." (PMID 32523084, 2020). "In addition to increased plasma lipid peroxide and urinary 8-isoprostane levels in stroke patients (group A), we have also detected significantly increased activities of antioxidant enzymes, SOD and catalase in lysates of erythrocytes." (PMID 27774120, 2016). "Previous research has also suggested that catalase activity may be more relevant in the early acute phase of stroke rather than during the later recovery phase examined in this study." (PMID 40837372, 2025). "Delving into oxidative stress markers, elevated TBARS levels in the Stroke-COVID group underscored the heightened state of cellular damage, complemented by increased antioxidant defense mechanisms, particularly in GSH, GPx, SOD, and CAT activities, compared to the control group." (PMID 38069113, 2023). "The meta-analysis of studies on biomarker changes after stroke rehabilitation revealed that rehabilitation can significantly increase the concentration of serum BDNF and NE, and peripheral blood SOD, ALB and HB, and CAT, and decrease the biomarkers of serum ET, glutamate, and TNF-α." (PMID 37731856, 2023). "Last, catalase activity and advanced oxidation protein products are not routinely examined in the clinical practice and these parameters are not available in most of the stroke centers, which might limit the formula for quantification of the edema for a widespread application." (PMID 35762501, 2023). "The multiple linear regression analysis was used to analyze age, gender, BMI, mRS, CAT, SOD, hydrogen peroxide, MDA, TNF-α, and IL-6 for factor independently correlated with HGS in non-paretic and paretic limbs of stroke patients." (PMID 33126675, 2020). "The serum levels of catalase activity and malondialdehyde (MDA), and plasma tumor necrosis factor (TNF)-α levels were significantly increased in post-stroke patients compared with non-stroke controls." (PMID 33126675, 2020). "According to the literature, in stroke, the SOD value does not vary, while the CAT value decreases." (PMID 25838867, 2015).